LDB1 (LIM domain binding 1)
Description:
Binds to the LIM domain of a wide variety of LIM domain-containing transcription factors. May regulate the transcriptional activity of LIM-containing proteins by determining specific partner interactions. Plays a role in the development of interneurons and motor neurons in cooperation with LHX3 and ISL1. Acts synergistically with LHX1/LIM1 in axis formation and activation of gene expression. Acts with LMO2 in the regulation of red blood cell development, maintaining erythroid precursors in an immature state.
Synonyms: LDB-1; CLIM-2; CLIM2; NLI
Tractability: Small molecule: a structure with a bound ligand is known. PROTAC: UniProt records ubiquitination sites on it; ubiquitination databases record sites on it; its protein half-life has been measured.
Gene: Protein-coding gene on chromosome 10 (102,106,489 to 102,120,368, reverse strand). Ensembl gene ENSG00000198728.
Subcellular location: Nucleus
Subcellular location (Human Protein Atlas): Nucleoplasm
Pathways (Reactome):
Developmental Biology: Cardiogenesis; Regulation of expression of SLITs and ROBOs
Gene expression (Transcription): RUNX1 regulates transcription of genes involved in differentiation of HSCs
Sensory Perception: Expression and translocation of olfactory receptors
Gene Ontology:
Molecular function: DNA-binding transcription factor binding; enzyme binding; LIM domain binding; protein binding; RNA polymerase II-specific DNA-binding transcription factor binding; protein homodimerization activity; chromatin binding; DNA binding; identical protein binding; transcription coactivator activity
Biological process: negative regulation of DNA-templated transcription; positive regulation of transcription by RNA polymerase II; negative regulation of erythrocyte differentiation; negative regulation of transcription by RNA polymerase II; nervous system development; neuron differentiation; positive regulation of hemoglobin biosynthetic process; positive regulation of transcription elongation by RNA polymerase II; regulation of cell migration; regulation of focal adhesion assembly; regulation of kinase activity; transcription-dependent tethering of RNA polymerase II gene DNA at nuclear periphery; head development; transcription by RNA polymerase II
Cellular component: beta-catenin-TCF complex; chromatin; transcription regulator complex; cell leading edge; nucleoplasm; nucleus; protein-containing complex; RNA polymerase II transcription regulator complex
Genetic constraint (gnomAD): Loss-of-function variants: 6 observed, 49.33 expected, observed/expected ratio (o/e) 0.12, 90% interval 0.066 to 0.24. The upper end of that interval is the gene's LOEUF score, 0.24, which puts it in group 1 of 6, group 1 being the genes least tolerant of losing a copy. Missense variants: 340 observed, 567.32 expected, observed/expected ratio (o/e) 0.6, 90% interval 0.55 to 0.66. Synonymous variants: 229 observed, 205.55 expected, observed/expected ratio (o/e) 1.11, 90% interval 1 to 1.24.
Homologues: Orthologues: chimpanzee LDB1 (100% identical), macaque LDB1 (100% identical), dog LDB1 (99% identical), pig LDB1 (99% identical), rat Ldb1 (99% identical), rabbit LDB1 (99% identical), tropical clawed frog ldb1 (98% identical), guinea pig LDB1 (98% identical), zebrafish ldb1b (95% identical), mouse Ldb1 (91% identical), zebrafish ldb1a (84% identical), Drosophila melanogaster Chi (60% identical), and 1 more. Paralogues in human: LDB2 (70% identical).
Diseases named in the same sentence as LDB1 in open-access papers:
LDB1 is named in the same sentence as 34 diseases in open-access papers, as found by Europe PMC text mining. Sharing a sentence is not in itself a finding about the gene and the disease. The quoted sentences say what the papers report.
leukemia (7 papers, 2016 to 2025). A malignant (clonal) hematologic disorder, involving hematopoietic stem cells and characterized by the presence of primitive or atypical myeloid or lymphoid cells in the bone marrow and the blood. "In conclusion, there is consistency between the results of the in vivo and in vitro experiments, which together prove that Ldb1 knockdown has an anti-tumor effect in leukemia." (PMID 37573405, 2023). "We further investigated the expression of LDB1 and its putative target genes in leukemia stem cells derived from AML patients, utilizing publicly available single-cell RNA sequencing (scRNA-seq) data obtained from AML patient." (PMID 37573405, 2023). "Gene concentration analysis (GSEA) revealed that genes related to leukemia apoptosis and tumor necrosis factor were more abundant in LDB1 knockdown cells than in the control cells." (PMID 37573405, 2023). "These 184 differential dependencies include genes known to be overexpressed or predictive of prognosis for the associated cancer type such as increased dependencies on LDB1 and LMO2 in leukemia." (PMID 35382456, 2022). "To summarize, this study demonstrates that LDB1 is a novel regulatory factor of leukemia." (PMID 37573405, 2023). "LDB1 could promote leukemia development by regulating LMO2 expression, and forming the LDB1/LMO2 protein complex in AML." (PMID 37573405, 2023). "LDB1 can stabilize direct and indirect binding partners and is the main core subunit that may be targeted in leukemia." (PMID 37573405, 2023). "Therefore, tackling the interplay between FLI-1 and the LDB1 complex in human primary cells will definitely validate its role in leukemia and megakaryopoiesis." (PMID 33733070, 2021). "In AML1-ETO leukemia, genomic data have suggested a functional complex among RUNX1, LDB1/LMO2, and HEB." (PMID 39450904, 2025). "Based on the expression of well-established leukemia stem cell signatures, leukemia cells from each patient into LSC-high or LSC-low groups and the expression of LDB1 target genes were compared." (PMID 37573405, 2023). "LDB1 is a key factor in the transformation of thymocytes into T-ALL induced by LMO2, and enhances the stability of carcinogenic related proteins in leukemia." (PMID 37573405, 2023). "Moreover, the steady-state abundance of LMO2 increases with co-expression of LDB1; hence, targeting LDB1/LMO2 becomes a treatment possibility for leukemia." (PMID 37573405, 2023). "Furthermore, LDB1 is a necessary partner of LMO2, especially when it comes to the T-ALL mouse model, confirming that Ldb1 plays a role in Lmo2-induced leukemia." (PMID 37573405, 2023). "The transcription factor complex of AML1-ETO fusion protein, consisting of AML1-ETO, LMO2, LDB1 and LYL1, has recently been considered the key to leukemia maintenance and differentiation blocking, because knockout of this complex can delay leukemogenesis in mice." (PMID 37573405, 2023). "Interestingly, previous studies have shown that the enhancer/promoter loop interactions required looping factor LDB1 and TAL1/GATA/LMO2 transcription super complexes that are present in both normal hematopoiesis and T-ALL leukemia." (PMID 32086528, 2020). "LDB1 is a key factor in thymocyte radiation resistance and tumor transformation into T-ALL induced by LMO2, which determines the key role of non-proto-oncogenes in leukemia." (PMID 37573405, 2023).
oral cancer (3 papers, 2003 to 2023). "Since LMO4 and LDB1 were expressed in oral carcinomas, we examined the binding between LMO4 and LDB1 proteins by immunoprecipitation." (PMID 12771919, 2003). "The absence of LDB1 could reduce the invasion and migration in oral cancer cell lines." (PMID 37573405, 2023).
acute myeloid leukaemia (2 papers, 2023 to 2025). "In acute myeloid leukaemia cells, the LMO2/LDB1 complex has an important role to promote cell growth and proliferation and is required for cell survival." (PMID 41385269, 2025).
colorectal cancer (2 papers, 2016 to 2021). A primary or metastatic malignant neoplasm that affects the colon or rectum. "In conclusion, LDB1 overexpression is a negative prognostic factor in colorectal cancer." (PMID 27713177, 2016).
squamous carcinoma (2 papers, 2003 to 2016). "The present study demonstrated that LMO4 and LDB1 form a protein complex and are overexpressed at the carcinoma invasive front, and in less-differentiated and metastasised squamous carcinoma cells." (PMID 12771919, 2003). "Prompted by the observation that LMO4 and LDB1 are expressed in embryonic epithelial tissues, we examined the expression pattern of LMO4 and LDBs in squamous carcinoma cells." (PMID 12771919, 2003). "There are currently no studies available investigating the correlation of LDB1 overexpression with metastatic activity; however, LDB1 overexpression at the invasive front of squamous cell carcinomas of the head and neck suggests a connection between LDB1 overexpression and metastasis." (PMID 27713177, 2016). "Expression of LMO4, LDB1, and LDB2 in squamous cell carcinomas has not been investigated." (PMID 12771919, 2003).
colorectal tumor (1 paper, 2016). "In an initial screening attempt to identify a possible role of LDB1 in CRC, LDB1 transcripts were measured in primary tumor and normal mucosa samples from 59 CRC patients of all stages, who underwent colorectal tumor resection at the Department of Surgery of University Hospital Heidelberg." (PMID 27713177, 2016).
head and neck squamous cell carcinoma (1 paper, 2025). A squamous cell carcinoma that arises from any of the following anatomic sites: lip and oral cavity, nasal cavity, paranasal sinuses, pharynx, larynx, and salivary glands. "In head and neck squamous cell carcinoma (HNSCC), LMO4 is overexpressed at tumor invasion fronts and in lymph node metastases, where it interacts with LIM domain-binding protein 1 (LDB1) and shows enhanced nuclear localization." (PMID 41213908, 2025).
hepatocellular carcinoma (1 paper, 2016). A malignant tumor that arises from hepatocytes. "In a chemically induced mouse model of hepatocellular carcinoma, hepatocyte-directed Ldb1 knockout lead to larger and more frequent tumors, which also displayed increased proliferation and resistance to apoptosis." (PMID 27713177, 2016). "Previous data from mouse models demonstrated a prominent role of Ldb1 in hepatocellular carcinoma and intestinal homeostasis, indicated an inhibition of Wnt signaling by Ldb1 and hence a tumorsuppressive role of Ldb1 overexpression." (PMID 27713177, 2016).
metastatic disease (1 paper, 2016). "To evaluate the influence of LDB1 expression on systemic tumor dissemination, we performed a subgroup analysis on patients with non-metastatic disease only." (PMID 27713177, 2016).
microphthalmia (1 paper, 2018). Congenital or developmental anomaly in which the eyeballs are abnormally small. "Retina-specific ablation of Ldb1 in mice resulted in microphthalmia, optic nerve hypoplasia, retinal thinning and detachment, and profound vision impairment as determined by electroretinography." (PMID 30127719, 2018).
nail-patella syndrome (1 paper, 2018). A rare hereditary patellar dysostosis characterized by nail hypoplasia or aplasia, aplastic or hypoplastic patellae, elbow dysplasia, and the presence of iliac horns as well as renal and ocular anomalies. "Mutations in the Ldb1 cofactor gene Lmx1b causes nail-patella syndrome, whose symptoms comprise part of the phenotypes found in Ldb1 mutants." (PMID 30127719, 2018).
neuroblastoma (1 paper, 2019). Neuroblastoma (NB) is the most common solid, extracranial childhood tumor. "Consistently, FLAG-tagged LMO1 could interact with endogenous GATA3 and LDB1 proteins when overexpressed in Kelly neuroblastoma cells." (PMID 31819055, 2019).
oral cavity carcinoma (1 paper, 2016). A carcinoma arising in the oral cavity. "A role for LDB1 and its LIM domain partner protein LMO4 in metastasis was suggested from the location of these proteins in oral cavity carcinoma, a finding which we extended to also include oropharyngeal carcinoma." (PMID 27780223, 2016).
oropharyngeal carcinoma (1 paper, 2016). Carcinoma, predominantly squamous cell, arising from the epithelial cells of the oropharynx. "The similarity in the frequency and localization of LMO4, LDB1, and SSBP2/3 expression in oral cavity and oropharyngeal carcinomas, by contrast, suggest these proteins subserve common functions in HNSCC regardless of etiology." (PMID 27780223, 2016).
rectal tumors (1 paper, 2016). "In addition, the association between LDB1 expression and Wnt signaling activity was stronger in tumors of the colon than rectal tumors." (PMID 27713177, 2016).
renal failure (1 paper, 2014). "In support of the role of LDB1 in LMX1B function, in mice specific inactivation of Ldb1 in podocytes leads to gradual loss of foot processes and GBM defects are found which lead to renal failure." (PMID 24809698, 2014).
stem cell leukemia (1 paper, 2023). "In erythroid differentiation, core transcriptional networks play crucial roles, which include gata binding protein 1 (GATA1), T-cell acute lymphoblastic leukemia/stem cell leukemia (TAL1/SCL), Krüppel-Like Factor 1 (KLF1), LIM domain only 2 (LMO2), and LIM domain binding protein 1 (LDB1)." (PMID 37296674, 2023).
T-cell leukemia (1 paper, 2023). A malignant disease of the T-lymphocytes in the bone marrow, thymus, and/or blood. "The nuclear adapter Ldb1 is required for Lmo2 oncogene-induced thymocyte self-renewal and T-cell leukemia in a mouse model of T-ALL." (PMID 37573405, 2023).
cancer (15 papers, 2003 to 2025). A tumor composed of atypical neoplastic, often pleomorphic cells that invade other tissues. "Meis1 and Fut8 gene, which are activated by Fli-1 and the LDB1 complex bound at their enhancer regions, encode two proteins, which have functions in different cancer." (PMID 33733070, 2021). "LDB1 regulates the differentiation of luminal cells in the gastrointestinal tract and cardiomyocytes and is also involved in cancer progression." (PMID 32745119, 2020). "Further studies should be addressed to demonstrate a direct role for LMO4 and LDB1 in carcinoma metastasis." (PMID 12771919, 2003). "Immunoprecipitation studies revealed that LMO4 and LDB1 interact with each other in the nuclear milieu of the carcinoma cells indicating the presence of an LMO4-LDB1-mediated transcription complex." (PMID 12771919, 2003). "Integration of the LDB1 regulatory network into the broader context of stem cell biology promises to advance our knowledge of stem cell fate decisions and inform the potential application of stem cells in treatment of genetic blood diseases and cancers." (PMID 40568081, 2025). "Finally, we demonstrate the involvement of LMO4 and LDB1 in cancer cell proliferation, invasiveness, migration, and angiogenesis, suggesting these nuclear proteins are important regulators of growth and metastasis in HNSCC." (PMID 27780223, 2016). "Both LMO4 and LDB1 proteins were preferentially localised in the nuclei of carcinoma cells at the invasive front and the immunoreactivity was increased in less-differentiated carcinoma tissues (P<0.01)." (PMID 12771919, 2003). "In the present study, our data demonstrate for the first time that LMO4 and LDB1 form protein complexes in the nucleus and are expressed in carcinoma cells at the invasive front, and their immunoreactivity is increased in less-differentiated carcinomas and in metastasised lymph nodes." (PMID 12771919, 2003). "The relatively increased expression of Wnt pathway genes in the LDB1-overexpressing, proximal (colon) cancer samples analyzed here may be a result of the higher LDB1 expression; this in turn can explain the increased clinical effects of LDB1 overexpression in proximal CRC samples." (PMID 27713177, 2016). "For instance, HMGB1, HMGB2, and MS4A1 were hypomethylated and highly expressed, whereas hypermethylation of genes such as LDB1, NDUFS2, and POU2F2 led to their reduced expression, reinforcing the impact of DNA methylation on gene dysregulation in cancer." (PMID 40396172, 2025). "LMO2-driven activation of STAT3 signaling requires the LDB1 protein and leads to increased expression of an inhibitor of differentiation 1 (ID1), a master regulator of cancer stemness." (PMID 35805116, 2022). "Carcinoma cells in the lymph nodes significantly increased the immunoreactivity of LMO4 (37.67±22.60) and LDB1 (38.07±23.84) compared to the corresponding primary sites (LMO4; 13.46±18.29, LDB1; 17.63±14.99)." (PMID 12771919, 2003). "LDB1, the homologous protein of LDB2, has been widely explored such as erythroid differentiation, embryogenesis, and cancer development, but the biological role of LDB2 bearing 78% identity and 89% similarity to the LDB1 is largely unknown." (PMID 36473369, 2023). "Thus, we provided compelling evidence demonstrating that the LDB1 contributes to tumorigenesis and poor prognosis in AML and can serve as a target for the development of cancer therapeutics." (PMID 37573405, 2023). "Although the molecular mechanism of LMO4–LDB1 complex formation in carcinoma dedifferentiation is not clearly defined yet, LMO4 acts as a dominant negative by interacting with LDB1, thereby competing for binding between LDB1 and transcription factors." (PMID 12771919, 2003).